SIRT1 (sirtuin 1)
Diseases named in the same sentence as SIRT1 in open-access papers (continued):
Sharing a sentence is not in itself a finding about the gene and the disease.
diabetes (continued). "Recent research has shown that Sirt1 protein expression and downstream signaling were downregulated in diabetes." (PMID 36360783, 2022). "Using a streptozotocin-induced diabetes mouse model, the authors found that treatment with bakuchiol increases SIRT1 levels and its deacetylase activity as well as Nrf2 nuclear accumulation in the diabetic myocardium." (PMID 35883477, 2022). "In diabetic and gestational diabetic patients SIRT1 downregulation, along with the downregulation of FKBP prolyl isomerase-like (FKBPL), has been linked to vascular dysfunctions and pregnancy complications both in vivo and in vitro." (PMID 35328633, 2022). "One beneficial role for SIRT1 in the context of diabetes, which requires further investigation, is the potential enhancement of insulin secretion." (PMID 36176467, 2022). "SiRT-1 regulates inflammation, metabolic pathways, cell survival, and cellular senescence and participate in the pathogenesis of chronic conditions such as diabetes as well as neurodegenerative, pulmonary, and cardiovascular diseases." (PMID 36301384, 2022). "Previous studies have highlighted the relevance of the SIRT1/PGC-1α pathway in the maintenance of testicular function of diabetic animals, and the depletion of SIRT1 and PGC-1α induced by diabetes lead to germ cells loss." (PMID 36012191, 2022). "Recently, melatonin has been shown to prevent Drp1-mediated mitochondrial fission through SIRT1-PGC1α pathway, which contributes to protection against diabetes-induced cardiac dysfunction." (PMID 35962432, 2022). "It has been established that HOTAIR is involved in hepatic insulin resistance via inhibiting sirtuin 1 (SIRT1), a potential therapeutic target to combat insulin resistance and diabetes, and suppressing the/Akt/glycogen synthase kinase-3β (GSK-3β) pathway." (PMID 35359879, 2022). "Turmeric-induced SiRT-1 upregulation has advantageous influence versus a wide range of maladies counting diabetes, cardiac fibrosis, and hepatic and ischemia/reperfusion injury." (PMID 36301384, 2022). "For instance, injection of resveratrol reduced oxidative stress and mitochondrial dysfunction in mouse models of diabetes through the activation of the AMPK/SIRT1/PGC-1α axis." (PMID 36262282, 2022). "Resveratrol can activate and upregulate NAD+ dependent SIRT1, thereby improving or delaying the development of diabetes, cardiovascular disease, cancer, and other diseases." (PMID 35739982, 2022). "Studies performed in a diabetes mouse model showed that curcumin treatment modulates SIRT1 through AMPK, thus contributing to an improved glucose absorption and metabolism." (PMID 35807694, 2022). "We investigated the effects of cilostazol on angiogenesis in diabetes in vitro and in vivo through adiponectin/adiponectin receptors (adipoRs) and the sirtuin 1 (SIRT1)/AMP-activated protein kinase (AMPK) signaling pathway." (PMID 36499166, 2022). "Quercetin, in diabetes, activates SIRT-1 leading to eNOS phosphorylation, NO production and intracellular cGMP in endothelial progenitor cells." (PMID 36496468, 2022). "Based on these findings, they proposed that lncRNA TUG1 promoted the browning of white adipose tissue by regulating miR-204/SIRT1 axis to ameliorate diabetes." (PMID 36555704, 2022). "Overexpression of SIRT1 in podocytes attenuates proteinuria and kidney injury in an animal model of diabetes." (PMID 35721758, 2022). "Generally, SIRT1 expression is reduced under the conditions of metabolic disorders, such as diabetes and cardiovascular disease." (PMID 36139886, 2022). "The SIRT1 activator resveratrol has been demonstrated to attenuate diabetes development in NOD mice, and familial mutations in SIRT1 are associated with an increased risk for T1D development in humans." (PMID 36176467, 2022).
diabetes (continued). "In contrast, inducible podocyte-specific SIRT1 overexpression in type 1 diabetic OVE26 mice attenuated the progression of diabetic glomerulopathy by reducing albuminuria and attenuating diabetes-induced podocyte loss and oxidative stress." (PMID 35277012, 2022). "The potential of resveratrol in activating SIRT1 and affecting metabolism and oxidative stress, also in the diabetes context, stimulated further research aiming at discovering novel small molecule sirtuin-activating compounds (STACs)." (PMID 35409409, 2022). "In fact, the increased life expectancy due to the epigenetic regulation of SIRT1 is due to the improvement of several metabolic and aging-related diseases, such as diabetes, NAFLD, cardiomyopathy, and neurodegenerative disorders." (PMID 35956321, 2022). "In the peripheral nervous system, activation of sirtuin 1 can improve insulin resistance, increase glucose sensing and insulin secretion and brain insulin resistance drives diabetes related cognitive decline by inhibiting sirtuin 1 signaling." (PMID 36012263, 2022). "The SIRT1-mediated signaling pathway in diabetes and cancer is the SIRT1/forkhead-box class O (FoxO)/nuclear factor-kappa B (NF-κB) pathway." (PMID 36430361, 2022). "Acacetin alleviates diabetes-accelerated atherosclerosis by preserving mitochondrial function via activating Sirtuin1 (Sirt1)/Sirtuin3 (Sirt3)/AMP-activated protein kinase (AMPK) pathway." (PMID 36299901, 2022). "Sirtuin 1 (SIRT1) is a NAD+-dependent deacetylase implicated in various biological and pathological processes, including cancer, diabetes, and cardiovascular diseases." (PMID 36235072, 2022). "It has been shown that activation of beta-adrenergic receptors can increase SIRT1 expression and diabetes-induced neuropathy like chemically-induced neuropathy and decreases SIRT1 expression." (PMID 36465704, 2022). "SIRT1 deacetylates FOXO4, decreasing the expression of the proapoptotic gene Bcl2l11, preventing podocyte loss in diabetes." (PMID 35277012, 2022). "SIRT1 expression in beta cells helps enhance insulin production to manage glucose levels and prevent the onset of diabetes." (PMID 36225477, 2022). "In a rat model of T2DM, a SIRT1 agonist (SRT1720) was shown to ameliorate the effects of diabetes-induced cognitive decline." (PMID 36295866, 2022). "Many commonly used agents for the treatment of type 2 diabetes mellitus can alter SIRT1 levels and activity." (PMID 36225477, 2022). "The aim of this study was to evaluate the concentration of sirtuin 1, visfatin, and IL-27 in relation to cardiovascular parameters and Hashimoto’s disease (HD) in young, asymptomatic women with type 1 diabetes mellitus (T1DM)." (PMID 34439776, 2021). "We have previously reported the cardioprotective effect of garlic and resveratrol against diabetes-induced oxidative stress via activation of Sirt1 and Sirt3, respectively." (PMID 33668369, 2021). "Mesenchymal stem cell-conditioned media can ameliorate diabetes-provoked endothelial dysfunction by improving mitochondrial function by the SIRT1-dependent PI3K/Akt/AMPK/PGC1α pathway." (PMID 34071497, 2021). "SIRTs activator, resveratrol, has been reported to improve diabetes-provoked cardiac dysfunction via activation of SIRT1 and SIRT3." (PMID 34071497, 2021). "Melatonin regulates the expression of DRP1 through the SIRT1-PGC1α cell signal transduction pathway to reduce mitochondrial fission and ultimately alleviate diabetes-induced cardiac insufficiency." (PMID 34660720, 2021). "It has been shown that one month after the onset of diabetes in rats, the expression of SIRT1 increases in the heart of animals, while three months later, the level of SIRT1 decreases." (PMID 34670596, 2021). "Previous studies indicated the role of SIRT1 in the protection of CR in various diseases, including diabetes and neurodegenerative diseases." (PMID 34712381, 2021).
diabetes (continued). "SIRT1 activation, in vivo, prevented diabetes-induced inflammation and vascular and neural degeneration." (PMID 33581416, 2021). "l-arginine has been proposed to trigger cardiac SIRT1 expression in diabetic rats and ensured defense against diabetes-mediated fibrosis, apoptosis, and inflammation in myocardial tissue." (PMID 34071497, 2021). "One of the key known regulators of physiological pathways involved in tumorigenesis, diabetes, and inflammatory diseases is SIRT1, a histone deacetylase that alters metabolic gene expression profiles." (PMID 34907162, 2021). "Sirt1 in tubular epithelial cell protects against albuminuria in diabetes by maintaining NMN concentrations around glomeruli, thus influencing podocyte function." (PMID 34485320, 2021). "In conclusion, placental FKBPL and SIRT-1 expression appears to be downregulated in response to diabetes in T1D and GDM, respectively, as well as following exposure to high glucose in trophoblast cells only in low oxygen conditions." (PMID 34149611, 2021). "Melatonin was proposed to ameliorate ischemia AKI in diabetes by improving the SIRT1/Nrf2/HO-1 signaling, suggesting that the SIRT1/Nrf2/HO-1 pathway can be a new target in decreasing the oxidative stress in diabetic IRI." (PMID 34063933, 2021). "Despite the numerous studies evaluating the effects of bioactive phytochemicals on cellular metabolic pathways, however, limited evidence is available regarding possible effects of betalains on AMPK and/or SIRT1 levels in diabetes." (PMID 34656137, 2021). "Previous evidences have suggested that the AMPK and SIRT1 signaling participate in alleviating diabetes and its correlation complications via reducing oxidant stress and apoptosis injury." (PMID 34336116, 2021). "It has reported that activation with SIRT1 played a critical role in alleviating diabetes and diabetic complications via decrease of oxidant stress." (PMID 34336116, 2021). "The current study for the first time indicated that betanin can play its protective roles via the regulation of AMPK/SIRT1/NF-κB signaling pathway in experimentally induced diabetes mellitus." (PMID 34656137, 2021). "A well-known SIRT1 activator—resveratrol (RES)—was shown to attenuate diabetes while SIRT1 knockdown leads to insulin resistance, enhanced cholesterol and free fatty acid levels." (PMID 34034759, 2021). "As stated by a prior study, increased inflammation is involved with the adipose tissue hypo‐expression of SIRT1, which exerts local and systemic effects and affect the cardiac performance in overweight patients with pre‐diabetes." (PMID 34541816, 2021). "Several studies have also shown that aberrant Sirtuin-1 signaling, when present in ECs (likely disease state such as diabetes or aging induced), upregulates several pathways that interfere with angiogenesis such as Notch and Wnt pathways." (PMID 34681756, 2021). "Diabetes mellitus-dependent downregulation of SIRT1 results also in increased acetylation of nuclear factor NF-kB p65, and increased nuclear translocation and transcription of inflammatory genes." (PMID 34698884, 2021). "MiR-22, the levels of which are decreased in diabetic myocardium in T1DM STZ-induced diabetes model, was found to target SIRT1 leading to the upregulation of SIRT1 protein expression." (PMID 33639953, 2021). "Taken together, our study reveals that GDF11 overexpression protects against diabetes-induced myocardial injury by attenuating cardiac fibrosis, oxidative stress, and cardiomyocyte apoptosis by activating the SIRT1 signaling pathway." (PMID 34262905, 2021).
diabetes (continued). "SIRT1 has been reported to attenuate neuropathic pain in diabetes through suppression of mGluR1/5 by facilitating H3 acetylation at the promoter region of mGluR1/5-encoding Grm1/5." (PMID 34071497, 2021). "Diabetes patients present reduced expression of sirtuin 1 (SIRT1) that is responsible for deacetylation of multiple proteins, including transcription factors essential, not only for metabolic machinery, but also for DNA repair." (PMID 34208589, 2021). "Consistent with this notion, a “proximal tubule-podocyte communication” has been inferred by which tubular sirtuin-1 is able to downregulate claudin-1 expression in podocytes and thus afford protection against diabetes-induced albuminuria." (PMID 32604897, 2020). "Numerous other miRNAs, including miR-195, miR-217, miR-155, miR-204-5p, and miR-211, were proven to trigger the downexpression of SIRT1 upon diabetes and its complications." (PMID 32962281, 2020). "In recent years, age-related diseases such as heart disease, neurological diseases, cancer, and diabetes have been found to be closely related to SIRT1, and similarly, SIRT1 has garnered considerable attention because of its role in the pathogenesis of asthma." (PMID 32823491, 2020). "Further, diabetes status reduced expression of SIRT1, HO-1, and p-AMPK in the heart, and ginkgolide B treatment significantly restored their expression in diabetic rats." (PMID 32952955, 2020). "Like SirT1, HO-1 confers protection in several vascular injury models, such us ischemic heart disease, atherosclerosis, hypertension, diabetes, or vascular proliferative diseases." (PMID 32982786, 2020). "SIRT1 regulates metabolic pathways, cell survival, cellular senescence, and inflammation, and acts in the pathogenesis of chronic conditions such as diabetes as well as pulmonary, neurodegenerative, and cardiovascular diseases." (PMID 32848804, 2020). "Previous studies showed that Sirt1 can regulate diabetes-induced cardiac dysfunction and brain ischemic reperfusion injuries by preventing mitochondrial dysfunction and alleviating hepatic steatosis." (PMID 32923413, 2020). "We previously showed that diabetes promotes retinal vascular senescence and this effect is associated with loss of the NAD + -dependent histone deacetylase sirtuin 1 (SIRT1) and up-regulation of senescence markers." (PMID 32660051, 2020). "Formononetin, a polyphenolic compound, is a molecule that increases the expression of SIRT1 in kidney tissues of diabetic patients and an effective molecule for controlling nephropathy in type 2 diabetes mellitus." (PMID 33178322, 2020). "Upregulation of sirtuin-1, a protein deacetylase, has been described to attenuate DN in different experiments reproducing diabetes conditions, as well as in mesangial cells, proximal tubular cells and podocytes." (PMID 32604897, 2020). "NMN treatment prevented the diabetes-induced decrease in both SIRT1 and PGC-1α and promoted deacetylation of proteins." (PMID 32466541, 2020). "Knockdown of Sirt1 in mice aggravates albuminuria and mitochondrial dysfunction in both diabetes- and adriamycin-induced podocyte injury, and this is due to reduced clearance of dysfunctional mitochondria by autophagy." (PMID 33321755, 2020). "In transgenic mice, moderate expression of SIRT1 improves the glucose tolerance and insulin sensitivity in addition to resistance toward diabetes." (PMID 32082101, 2020). "When only Group A and Group B were considered, the differences in the expressions of ALOX5, LTB4R, DDOST, and SIRT1 mRNAs were maintained after adjustment for sex, age, diabetes duration, and use of ACEI, ARB, and statin (P < 0.0001 for all genes)." (PMID 32273829, 2020). "The hyperglycemia, hyperlipidemia, and inflammatory cytokines in diabetes can likely increase oxidative stress and decrease silent mating type information regulation 2 homolog 1 (sirtuin 1 [SIRT1]) levels." (PMID 32033527, 2020).
diabetes (continued). "They observed that in diabetes mellitus, SIRT1 activity was reduced by PARP-1 activation and NAD+ depletion due to low concentration of AMPK increasing NOX4 expression." (PMID 32013273, 2020). "The downregulation of SIRT1 and AMPK has been shown to cause cardiomyopathy in experimental models of diabetes, whose features are characterized by oxidative stress and organellar dysfunction." (PMID 32404204, 2020). "Previous studies have reported that SIRT1 upregulation protects against diabetes-induced liver toxicity." (PMID 32365537, 2020). "Another study showed that the increased MMP-9 was attenuated by not only the SIRT1 activator resveratrol, but also by the diabetes drug metformin in a mouse model exposed to UV light." (PMID 32823491, 2020). "Initial research revealed a significant role of SIRT1 signaling in mediating the antioxidant effect of BBR in diabetes and in lipid metabolism." (PMID 32848804, 2020). "Among the seven mammalian sirtuins (referred to as SIRT1-7), SIRT1 has been most extensively investigated and is proposed to be involved in a variety of human diseases, including diabetes, cancer and cardiovascular disorders." (PMID 32003755, 2020). "The expression levels of SIRT1 mRNA were significantly increased in the serum of patients with diabetes compared with the normal participants (P<0.001)." (PMID 32627000, 2020). "We found decreased SIRT1 levels in patients with increased urinary albumin excretion (UAE), the lowest with diabetes presence, and a strong association with UAE, discriminating incipient renal damage." (PMID 32887498, 2020). "In a mouse model of STZ‐induced diabetes, SIRT1 and NRF2 antioxidant signalling were less expressed in the kidneys of the diabetic mice compared with non‐diabetic control mice." (PMID 32628815, 2020). "The expression and activity of SIRT1 are reduced in hunger, calorie restriction, and some chronic diseases such as diabetes." (PMID 32033527, 2020). "There is a functional link between HMGB1 and SIRT1 in the regulation of the diabetes-induced breakdown of the BRB." (PMID 32722545, 2020). "Our results suggested that acacetin reduced vascular endothelial injury induced by high glucose and attenuated diabetes-accelerated atherosclerosis by Sirt1-mediated activation of Sirt3/AMPK signals." (PMID 33519472, 2020). "Administration of NMN to the Diabetic rats normalized the diabetes-induced decreases in both SIRT1 and PGC-1α and decreased acetylation of neuronal proteins." (PMID 32466541, 2020). "The aim of our study was to evaluate the role of sirtuins, particularly SIRT1, in the pathomechanism of diabetes and diabetic cardiomyopathy, and in addition to investigate the effect of Equisetum arvense L. extract effects in pathological conditions." (PMID 32486051, 2020). "It was observed that the activation of PARP-1 and the decrease of the levels of NAD+ and SIRT1 in diabetes were dose-dependent with oral administration of polyphenolic cocoa extract." (PMID 32013273, 2020). "SIRT1 belongs to the class of histone deacetylases and has attracted much attention in medical research fields such as diabetes, cardiovascular and cerebrovascular diseases, and tumors." (PMID 33762927, 2020). "There is increasing evidence of the anti-fibrotic effects of sirtuin-1 in experimental models of diabetes." (PMID 30707256, 2019). "We conclude that NOX4/UCP2/NF-κB and Sirt1/FOXO3a signaling pathways mediate the renal effects of PRR in diabetes." (PMID 31406124, 2019). "The available evidence implies that sirtuin-1 has great potential as a clinical target for the prevention and treatment of diabetes." (PMID 30707256, 2019). "Levels of serum SIRT1 were found to be six-fold lower in patients with diabetes (2.076 ng/mL SEM±1.036) compared to healthy controls (15.76 ng/mL SEM±2.184)." (PMID 30696833, 2019). "Our findings suggest that resveratrol provides a protective effect in the animal model of combined diabetes and AD via activation of Sirt1 and its downstream targets." (PMID 32038127, 2019).